CASC9 (cancer susceptibility 9)
Diseases named in the same sentence as CASC9 in open-access papers (continued):
Sharing a sentence is not in itself a finding about the gene and the disease.
glioma (10 papers, 2018 to 2024). A benign or malignant brain and spinal cord tumor that arises from glial cells (astrocytes, oligodendrocytes, ependymal cells). "The expression of lncRNA CASC9 (cancer susceptibility candidate 9) is significantly increased in glioma tissue and is positively related to advanced pathological grade of glioma." (PMID 34425834, 2021). "To identify the underlying mechanism that CASC9 accelerated the tumourigenesis of glioma, we sequentially performed mechanical experiments." (PMID 30270508, 2018). "After literature retrieval, 3 lncRNAs (RMRP, HOXA-AS3, and CASC9) related to glioma tumorigenesis and progression were screened out for further investigations." (PMID 34657141, 2021). "In this study, we investigate the roles of lncRNA CASC9 on glioma tumourigenesis and authenticate its potential mechanisms." (PMID 30270508, 2018). "Among these glioma tissue specimens, CASC9 expression was markedly up‐regulated in advanced pathological type (WHO III‐IV) than that of primary pathological type (WHO I‐II)." (PMID 30270508, 2018). "In order to test the role of miR‐519d and CASC9 on glioma, we further discovered the downstream target of miR‐519d." (PMID 30270508, 2018). "Results manifested that CASC9 was highly expressed in glioma specimens and cells, moreover, the ectopic overexpression was correlated with glioma patients’ clinic." (PMID 30270508, 2018). "Clinically, the aberrant overexpression of CASC9 was correlated with the clinical of glioma patients, implying the tumour promoting biomarker of CASC9." (PMID 30270508, 2018). "Firstly, the subcellular location of CASC9 is in the cytoplasm, indicating the post‐transcriptional control of CASC9 in the glioma cells." (PMID 30270508, 2018). "We confirmed that CASC9 is not only closely correlated with the clinical phenotype of glioma patients, but also involved in the molecular level of cells’ invasion and metastasis." (PMID 30270508, 2018). "Results revealed that CASC9 expression was markedly overexpressed in the collected glioma tissue specimens compared with adjacent normal tissue." (PMID 30270508, 2018). "Knocking down lncRNA CASC9 inhibits glioma cell invasion and proliferation." (PMID 34425834, 2021). "Moreover, GEPIA database analyses revealed that expression levels of RMRP, HOXA-AS3, and CASC9 were notably up-regulated in glioma tissues than in normal tissues." (PMID 34657141, 2021). "LncRNA CASC9 facilitates glioma tumorigenesis by sponging miR-519d30." (PMID 33298846, 2020). "Therefore, the cellular functions of CASC9 are clearly considered as oncogene in glioma tumourigenesis." (PMID 30270508, 2018). "As a first attempt to explore whether lncRNA CASC9 participated the pathogenesis of glioma, we measured the expression level of lncRNA CASC9 to identify whether it was aberrantly expressed in glioma tissue specimen." (PMID 30270508, 2018). "Overall, these data and finding could powerfully support the conclusion that CASC9 promotes the glioma tumourigenesis in vitro and in vivo." (PMID 30270508, 2018). "RT‐PCR revealed that lncRNA CASC9 expression was significantly up‐regulated in glioma cell lines." (PMID 30270508, 2018). "In conclusion, our results indicate that lncRNA CASC9 is highly expressed in glioma tissue." (PMID 30270508, 2018). "Clinically, we found that CASC9 was highly expressed in glioma tissue." (PMID 30270508, 2018). "Among others, STAT3 promotes CASC9 expression, essential lncRNA in glioma cells, which upregulates the expression of STAT3 via sponging miR-519d, generating a positive feedback loop of STAT3/CASC9/miR-519d." (PMID 39188680, 2024). "LncRNAs CASC9 and miR155HG promote STAT3 through the ceRNA mechanism, and STAT3, in turn, acts as a transcription factor in the nucleus of glioma cells to promote the expression of CASC9 and miR155HG." (PMID 34425834, 2021).
glioma (continued). "Taken together, in glioma, lncRNA CASC9 increases STAT3 expression by sponging miR‐519d, while STAT3 interacts with the CASC9 promoter to accelerate CASC9 expression." (PMID 34425834, 2021). "Given the association of tumor recurrence and drug resistance, expression patterns of RMRP, HOXA-AS3, and CASC9 were examined in tumor tissues isolated from glioma patients without any treatment (n = 20) and glioma patients suffered from recurrence post-treatment (n = 12)." (PMID 34657141, 2021).
hepatocellular carcinoma (10 papers, 2019 to 2025). A malignant tumor that arises from hepatocytes. "For example, lncRNA CASC9 targeting miR-424-5p affects the proliferation, apoptosis, and migration of hepatocellular carcinoma cells." (PMID 40859288, 2025). "Cancer susceptibility candidate 9 (CASC9) has been found to be upregulated in hepatocellular carcinoma compared to normal healthy controls and levels of expression in HCC may also be predictive of metastasis and prognosis." (PMID 33126510, 2020). "In contrast, CASC9 was detected mainly in the cytoplasm of hepatocellular carcinoma cells and in the nucleus of lung adenocarcinoma cells." (PMID 31186036, 2019). "A previous study has demonstrated that low CASC9 expression in hepatocellular carcinoma (HCC) had a better prognosis, which was consistent with our results in LIHC." (PMID 36445051, 2023). "A previous study identified CHEK1 as a target of miR-497 in hepatocellular carcinoma, and CHEK1 is the target gene of lncRNA CASC9/miR-497 axis in BC." (PMID 32766141, 2020).
lung carcinoma (9 papers, 2014 to 2023). "Cancer susceptibility candidate 9 (CASC9) was shown to be significantly upregulated in both lung cancer and nasopharyngeal carcinoma cell lines and tissues." (PMID 32640630, 2020). "Moreover, CASC9 overexpression was associated with proliferation and metastasis in lung cancer and enhanced glycolysis nasopharyngeal carcinoma." (PMID 32640630, 2020). "LncRNA CASC9 was found to be overexpressed in lung cancer tissues, and overexpressed CASC9 significantly increased the EMT, invasion, and migration abilities of tumor cells." (PMID 36139386, 2022). "It was demonstrated that CASC9 can be induced by HIF-1α and promote the stability of HIF-1α, indicating that HIF-1α and CASC9 can form a mutual activation pathway to promote the progression of lung cancer (Table A1)." (PMID 36139386, 2022). "Forced lncRNA CASC9 expression promotes NSCLC cell proliferation and chemoresistance via epigenetic repression of DUSP1, and univariate and multivariate analyses reported that lncRNA CASC9 can be regarded as independent prognostic markers in lung cancer." (PMID 35685240, 2022).
nasopharyngeal carcinoma (8 papers, 2018 to 2022). A carcinoma arising from the nasopharyngeal epithelium. "Another HIF-1α binding lncRNA CASC9 (cancer susceptibility candidate 9) is highly expressed in nasopharyngeal carcinoma (NPC) tissues." (PMID 32370770, 2020). "In order to further explore the effect of CASC9 on the growth of nasopharyngeal carcinoma cells in vivo, HONE-1 cells transfected with sh-CASC9 or sh-NC were introduced into nude mice." (PMID 35419295, 2022). "Mechanism research confirmed CASC9 regulated the malignant biological behavior of nasopharyngeal carcinoma cells by targeting miR-497-5p/Wnt3a/β-catenin signaling pathway." (PMID 35419295, 2022). "In nasopharyngeal cancer, CASC9 promotes cell proliferation by hypoxia-inducible factor-1α." (PMID 35427373, 2022). "CASC9 may regulate the malignant biological behavior of nasopharyngeal carcinoma cells by targeting miR-497-5p/Wnt3a/β-catenin signaling pathway." (PMID 35419295, 2022). "Interestingly, in an RNA pull-down assay, CASC9 was demonstrated to directly bind to the HIF-1α protein in nasopharyngeal carcinoma, subsequently enhancing its stability." (PMID 32640630, 2020).
glioblastoma (6 papers, 2014 to 2024). The most malignant astrocytic tumor (WHO grade IV). "N6-methyladenosine (m6A) has been identified to exert critical roles in human cancer; however, the regulation of m6A modification on glioblastoma multiforme (GBM) and long non-coding RNA (lncRNA) CASC9 (cancer susceptibility 9) is still unclear." (PMID 34645788, 2021). "CASC9 RNA is highly expressed in glioblastoma in its m6A modified form: m6A reader IGF2BP2 stabilizes CASC9 RNA, so that CASC9 may increase hexokinase 2 (HK2) mRNA stability and consequently HK2 activity." (PMID 39280246, 2024). "In glioblastoma (GBM), lncRNA CASC9 can promote glycolysis and is related to the poor prognosis of GBM." (PMID 37582735, 2023). "In glioblastoma, IGF2BP2 recognizes the m6A site of lncRNA CASC9 and increases its stability, and CASC9 cooperates with IGF2BP2 to form a complex that stabilizes hexokinase 2 (HK2), promoting aerobic glycolysis." (PMID 35541906, 2022).
lung adenocarcinoma (6 papers, 2018 to 2022). A carcinoma that arises from the lung and is characterized by the presence of malignant glandular epithelial cells. "In adenocarcinomas of the lung increased CASC9 expression was also associated with tumor size, stage, lymph node metastasis and a poor prognosis." (PMID 31412811, 2019). "In LUAD, candidate driver lncRNA CASC9 was associated with the hallmark ‘Self Sufficiency in Growth Signals’, which could be confirmed by the phenomena that CASC9 promoted lung adenocarcinoma cell proliferation." (PMID 30216655, 2018). "CASC9 also regulates cell cycle progression in the G1 phase via cyclin D1 in lung adenocarcinoma." (PMID 35427373, 2022).
non-small cell lung carcinoma (6 papers, 2021 to 2023). A group of at least three distinct histological types of lung cancer, including non-small cell squamous cell carcinoma, adenocarcinoma, and large cell carcinoma. "MiR-335-3p inhibition by upregulated lncRNA CASC9 promoted proliferation, migration, and invasion of non-small cell lung cancer." (PMID 36354672, 2022). "CASC9 promotes the progression of non-small cell lung cancer through the miR-335-3p/S100A14 axis." (PMID 34101736, 2021). "In addition, a report also found that CASC9 could promote non-small cell lung cancer progression via miR-335-3p/S100A14 axis." (PMID 35419295, 2022).
oral squamous cell carcinoma (6 papers, 2019 to 2024). "ARlncRNA CASC9 was substantially expressed in oral squamous cell carcinoma and significantly linked with tumor volume, local lymph node migration, stage of the disease, and overall survival." (PMID 37588204, 2024). "In oral squamous cell carcinoma, overexpression of ARlncRNA CASC9 can suppress autophagy-mediated apoptosis through the AKT/mTOR, hence boosting tumor growth." (PMID 37588204, 2024). "Therefore, CASC9 could be a potential marker for the diagnosis and prognosis of oral squamous cell carcinoma." (PMID 37588204, 2024). "However, the expression and biological functions of CASC9 in oral squamous cell carcinoma (OSCC) remain unknown." (PMID 30674868, 2019). "New research has shown that the lncRNA CASC9 is upregulated in oral squamous cell carcinoma (OSCC), and knocking down CASC9 in OSCC cells significantly increases autophagy." (PMID 38933333, 2024). "The expression of CASC9 in normal oral mucosal cell HOMEC cell and oral squamous cell carcinoma cells, including TSCCA, SCC15 and CAL27 was further detected by RT-qPCR." (PMID 30674868, 2019). "Long non-coding RNA (lncRNA) CASC9 is reported to be a tumor promoter in oral cancer, but its mechanism in oral squamous cell carcinoma (OSCC) has not been fully explored." (PMID 34612783, 2021).
ovarian carcinoma (6 papers, 2019 to 2025). A malignant neoplasm originating from the surface ovarian epithelium. "The long noncoding RNA cancer susceptibility 9 called CASC9 is significantly highly expressed in ovarian cancer tissues and cells and correlates with poor prognosis in ovarian cancer patients." (PMID 40801824, 2025). "The CASC9/miR‐758‐3p/LIN7A axis has been shown to be involved in ovarian cancer progression, accelerating tumour proliferation in vivo." (PMID 40801824, 2025). "In turn, the inhibitory effect on ovarian cancer progression following CASC9 reduction could be reversed by LIN7A overexpression." (PMID 40801824, 2025). "CASC9/miR-758-3p/LIN7A pathway was identified in ovarian cancer progression." (PMID 35427373, 2022). "Furthermore, the expression levels of these upstream lncRNAs were detected by GEPIA, and the study demonstrated that only FUT8-AS1, CASC9, LINC00665, LINC01535, PART1 and LINC00511 were upregulated in ovarian cancer compared with normal samples." (PMID 33123295, 2020).
Sepsis (6 papers, 2021 to 2025). Sepsis is defined as life-threatening organ dysfunction caused by a dysregulated host response to infection. "Other studies have substantiated that miR-195-5p is overexpressed in lung tissues of sepsis rats, and the up-regulation of cancer susceptibility candidate 9 (CASC9) improves sepsis-induced acute lung injury (ALI) by inactivating the miR-195-5p/PDK4 axis." (PMID 34790697, 2021). "On the other hand, the downregulation of CASC9 upregulates miR-195-5p expression and aggravates sepsis-induced ALI." (PMID 36675533, 2023). "Protective lncRNAs can alleviate sepsis-induced renal injury through their upregulation; for instance, overexpression of CASC9 reduces cellular inflammation and apoptosis both in vivo and in vitro, enhances cellular antioxidant capacity, and diminishes sepsis-induced renal injury." (PMID 40657645, 2025). "CASC9 has been reported to play a protective role in sepsis-induced organ damage." (PMID 40657645, 2025). "Up-regulation of CASC9 promoted viability in sepsis-inducedALI." (PMID 34956235, 2021). "Additionally, CASC9 and TUG1 alleviated the sepsis-induced ALI via affecting the miR-195-5p/PDK4 axis and miR-34b-5p/GAB1 axis." (PMID 34126975, 2021). "Thus, CASC9 negatively regulates miR-195-5p/PDK4 axis and hinders sepsis-induced ALI." (PMID 36675533, 2023). "Moreover, miR-195-5p, which is generally involved in inducing and worsening ALI triggered by sepsis through inhibition of PDK4, could be stopped and downregulated by lncRNA CASC9." (PMID 36012630, 2022).
cervical cancer (3 papers, 2020 to 2024). A primary or metastatic malignant neoplasm involving the cervix. "Cancer susceptibility candidate 9 (CASC9) is another example of a ceRNA in cervical cancer." (PMID 33050576, 2020). "For example, CASC9 exhibits oncogenic function, and the CASC9-1 transcript is overexpressed in cervical cancer cells to increase proliferation by sponging miR-383-5p, which is reversed by CASC9 knockdown." (PMID 37190145, 2023). "CASC9 is increased in cancer tissues compared to normal tissues, and cervical cancer patients with low CASC9 expression have better overall survival rates than those with high CASC9 expression." (PMID 33050576, 2020). "TGF-β released from CAFs elevates CASC9 expression in cervical cancer cells." (PMID 33050576, 2020). "Thus, signaling from CAFs (TGF-β) contributes to cervical cancer progression via the regulation of CASC9/miR-215/TWIST2 signaling in cancer cells." (PMID 33050576, 2020).
colon cancer (3 papers, 2014 to 2024). "Finally, qRT-PCR analyses in colon cancer cell lines revealed elevated levels of lncRNAs CASC9, ZEB1-AS1, ATP2A1-AS1, SNHG7, AL683813.1, and AP003555.1, and reduced levels of FAM160A1-DT and AC112220.2, compared to normal cell lines." (PMID 39115621, 2024). "The analysis showed high expression of CASC9, ZEB 1-AS1, ATP2A1-AS1, SNHG7, AL683813.1 and AP003555.1 in colon cancer tissues, while FAM160A1-DT, AC112220.2 showed higher expression in normal tissues than in cancer tissues." (PMID 39115621, 2024).
lymph node metastasis (3 papers, 2019 to 2023). "Highly expressed CASC9 is strongly associated with tumor size, clinical stage, regional lymph node metastasis and overall survival time in OSCC patients." (PMID 30674868, 2019).
oral cancer (3 papers, 2020 to 2022). "Other lncRNAs frequently associated with oral cancers are lncRNA cancer susceptibility candidate 9 (lncRNA CASC9) and lncRNA HOTAIR, which was described as an oncogene that boosts the invasive and metastatic potential of OSCC." (PMID 35955417, 2022). "lncRNA CASC9 is a tumor promoter in oral cancer, but its regulatory mechanism involving the downstream key miRNA/mRNA axis is still unclear." (PMID 34612783, 2021). "LncRNA CASC9 was overexpressed in OSCC tissue and SCC15, TSCCA, and CAL27 oral cancer cell lines compared with healthy matched tumorous tissue and HOMEC, a normal cell line derived from oral keratinocytes." (PMID 35955417, 2022).
thyroid cancer (3 papers, 2019 to 2021). "Cancer susceptibility 9 (CASC9) is another example of a dysregulated ncRNA in thyroid cancer." (PMID 33158279, 2020). "In contrast, significant downregulation of CASC9 was found in the pan-cancer TCGA data in renal cell carcinoma (KIRC, KICH, KIRP), thyroid cancer (THCA), and prostate cancer (PRAD)." (PMID 31412811, 2019).
Cirrhosis (2 papers, 2018 to 2024). A chronic disorder of the liver in which liver tissue becomes scarred and is partially replaced by regenerative nodules and fibrotic tissue resulting in loss of liver function. "To start understanding the roles of deregulated expression of these lncRNAs in HCC and cirrhosis, we evaluated the associations between LUCAT1 and CASC9 expression and clinical-pathological variables." (PMID 30416681, 2018). "Notably, a trend towards a decrease in CASC9 and LUCAT1 was observed from healthy liver to cirrhosis without HCC and to cirrhosis complicated by HCC, in line with its possible contribution to hepatocarcinogenesis." (PMID 38398157, 2024). "A trend towards a decrease of CASC9 and LUCAT1 was observed, starting from healthy liver, to cirrhosis without HCC, to cirrhosis complicated by HCC with LUCAT1 displaying a relevant down-regulation in cirrhosis complicated by HCC, in line with its possible contribution to hepatocarcinogenesis." (PMID 30416681, 2018).
liver cancer (2 papers, 2022 to 2025). An epithelial or non-epithelial malignant neoplasm that arises from the liver. "Among the five DELs, CASC9, ZFPM2-AS1, and LINC00665 have been reported to influence the biological behavior of liver cancer cells 11-13." (PMID 35154469, 2022).
pancreatic cancer (2 papers, 2021 to 2024). "Moreover, the growth and metastasis of pancreatic cancer are impeded by silencing CASC9, suggesting that CASC9-induced glycolysis is responsible for pancreatic cancer malignancy." (PMID 34298879, 2021). "Further, it was connoted that CASC9, a hypoxia-inducible lncRNA, is regulated by HIF-1α and drives glycolysis via the upregulation of hexokinase 2 (HK2), lactate dehydrogenase A (LDHA), and glucose transporter type 4 (GLUT4) levels in pancreatic cancer." (PMID 34298879, 2021).
prostate carcinoma (2 papers, 2014 to 2019). A carcinoma that arises from epithelial cells of the prostate gland. "(b) Relative expression of CASC9 in prostate cancer cell lines, benign control cells (PREC, PNT-2, BPH-1) as well as normal (N) and cancerous (T) tissue." (PMID 31412811, 2019).
squamous carcinomas (2 papers, 2016 to 2019). "CASC9 may therefore be useful as a general diagnostic biomarker for cancers and particularly squamous cell carcinomas of different organs, like esophagus, head- and -neck, cervix and lung." (PMID 31412811, 2019). "Nevertheless, our analysis of TCGA pan-cancer data and various cell lines indicated that CASC9 is upregulated across cancers of various organs and in further squamous carcinomas." (PMID 31412811, 2019). "Collectively, these findings indicate CASC9 as a valuable diagnostic marker particularly for HNSCC and other squamous cell carcinomas." (PMID 31412811, 2019). "An important question for future work is therefore which factors drive the overexpression of CASC9 in HNSCC and other squamous cell carcinomas." (PMID 31412811, 2019). "CASC9 is robustly overexpressed in HNSCC, a promising candidate for tumor detection, and potentially of squamous cell carcinomas in all organs." (PMID 31412811, 2019).